CD163 (CD163 molecule)
Diseases named in the same sentence as CD163 in open-access papers (continued):
Sharing a sentence is not in itself a finding about the gene and the disease.
tumor (continued). "As a pleiotropic immunomodulatory molecule, CD163 not only stimulates the immune response but also promotes tumor cell proliferation, invasion and metastasis 26-27." (PMID 40092698, 2025). "The presence of CD86+ CD206+ TAMs has been shown to serve as a prognostic marker for iCCA, whereas the presence of CD163+ macrophages was correlated with worse overall survival in a retrospective study of human tumor samples." (PMID 40721870, 2025). "Immunofluorescence co-localization analysis showed that TLR9 was co-localized with CD163+ macrophages in tumor tissues from HCC patients." (PMID 40038250, 2025). "There was also only a limited match between IBA1 and CD163 immunoreactivity in numerous areas within the same tumor." (PMID 40191733, 2025). "Tumor-associated macrophages (TAMs), particularly the M1 (CD68+) and M2 (CD163+) subtypes, play critical roles in inflammation, fibrosis, and immune modulation." (PMID 41239536, 2025). "We established a 7-plex mIF panel to detect lymphoid aggregates and TLS using markers against T cells (CD3), B cells (CD20), mature dendritic cells (Lamp3), macrophages (CD163), as well as endothelial cells (vWF) and tumor cells (pan-cytokeratin or MelA)." (PMID 40319321, 2025). "We found that TMEM115 protein levels in tumor tissues were positively associated with CD68+ (R = 0.283, P < 0.001) and CD68+CD163+ (R = 0.145, P = 0.046) macrophages." (PMID 40552281, 2025). "On the other hand, in cancer samples, elevated expression levels of macrophage markers, particularly CD163, suggest a predominance of M2 TAMs within the tumour microenvironment (TME) of ccRCC." (PMID 40134439, 2025). "Among the significant findings identified by SpatioMark is under expression of CD163 by macrophages near tumours." (PMID 40674581, 2025). "In vivo, ONA administration not only reduced tumor growth and prolonged survival but also decreased the infiltration of pro-tumor CD163+ macrophages in tumor tissues." (PMID 40330466, 2025). "One study focused on expression in the entire tumor area, and found better survival related to high CD163 expression (100%)." (PMID 39904885, 2025). "Multiplex immunofluorescence revealed CD18 localization predominantly in CD163+ or CD206+ macrophages (Primary Tumor: n = 35), with strong positive correlation between COL10A1 and CD18 expression (R > 0.5, P < 0.001)." (PMID 40826474, 2025). "In total, the tumor area was accumulated with fibroblasts and endothelial cells and absent of immune cells, except T3 showing high expression of CD163, the marker of myeloid cells." (PMID 39670859, 2025). "We aim to determine changes and distribution of CD163+ immune cells during tumor progression from primary tumors (PT) to lymph node metastases (LNM) and distant metastases (DM)." (PMID 39751847, 2025). "Specifically, the presence of CD163+ and CD204+ TAM subsets is correlated with poor clinical outcomes, as the populations are implicated in rapid tumor proliferation and poor differentiation." (PMID 41417432, 2025). "In the present study, a significant correlation was found between a high expression of CD163 in the primary tumor stroma and a shorter RFS." (PMID 40510346, 2025). "CD163+ cells were quantified in both the tumor body (TB) and the invasive front (IF) of each ALM biopsy." (PMID 40362334, 2025). "In our case, CD4, CD68, and CD163 were all positive, and Lysozyme showed a small amount of sporadic positive expression, suggesting that the tumor cells originated from histiocytes." (PMID 40231251, 2025). "In conjunction with previous GEX analyses of the original cohort for PAM50 classification and evaluation of changes in GEX patterns during tumor progression, we also obtained information regarding CD163 GEX on the same matched material." (PMID 39751847, 2025). "Silencing CD163 in macrophages removes their ability to induce tumor growth, highlighting the receptor’s critical role in macrophage-mediated tumorigenesis." (PMID 40423041, 2025).
tumor (continued). "Within the chondrosarcoma TME, cytotoxic CD8+ T cells and CD163+ TAMs represent the two predominant immune populations, predominantly localized at the tumor margins and exerting opposing effects on tumor progression." (PMID 41357670, 2025). "The distribution of immune cell populations in the TME also changed depending on the tumor size analyzed, with the MDA-MB-231 tumor being mainly composed of M2-like macrophages (CD206+/CD163+) (93% at 200 mm3 vs 76% at 800 mm3)." (PMID 41041306, 2025). "Stroma cell labeling indices of CD4**, CD8*, Foxp3*, CD68*, CD163**, and CD11c* were significantly higher in both the tumor core and the invasive front of cSCC samples as compared to BCC (*p < 0.001; **p < 0.050)." (PMID 41068337, 2025). "We then further analyzed by flow cytometry monocyte/NEC or TEC cocultures, and particularly the CD31−CD45+ cell fraction for pro-tumor M2-like (CD163) and anti-tumor M1-like (HLA-DR) macrophage markers." (PMID 41310721, 2025). "Further analysis revealed significant H3K18la signals at the promoters of CD163 and other immunosuppressive genes, suggesting that tumor‐derived NDRG1 regulates the expression of these genes through lactate‐dependent H3K18la modifications." (PMID 40539245, 2025). "Survival was significantly longer in patients with higher baseline tumor infiltration of CD163 + macrophages and natural killer cells and in patients with reduced on-treatment circulating IL-6 levels or neutrophil-to-lymphocyte ratio." (PMID 40310569, 2025). "Our in vivo studies revealed that HCC/macrophage co-xenografts exhibited accelerated growth with enhanced M2 polarization, evidenced by an increased number of CD163+/Arg-1+ macrophages in tumor." (PMID 40453717, 2025). "The presence of intense M2 macrophage infiltration (CD68+ or CD163+) in the tumor stroma was a poor prognostic factor and correlated with shorter disease-free survival (DFS) and OS, although the opposite tendency was observed at TF." (PMID 40508145, 2025). "Increased CD163+ and CD68+ cell count (representing M2 type macrophages and all tumour associated macrophages respectively) and increased MCSF and CCL2 expression, in both LARC biopsy and resection specimens, were associated with inferior overall survival." (PMID 41487587, 2025). "The Wilcoxon test revealed a significant difference in the expression of the markers CD68, CD86, and CD163 between the tumor nest and tumor stroma in both the primary tumor and brain metastases across the overall cohort (p < 0.0001)." (PMID 40510346, 2025). "For immunohistochemistry to detect components of the tumor microenvironment, we analyzed the distributions of PD-L1, markers of tumor-associated fibroblasts (SMA), markers of TAMs (CD163 and CD68), in the tumor and adjacent normal tissue." (PMID 40416971, 2025). "Histopathological analysis revealed that combined therapy induced tumor stromal remodeling, evidenced by 74% reduction in Ki-67+ proliferating tumor cells and 65% decrease in CD163+ M2-like TAMs density." (PMID 40808689, 2025). "An independent study reported a higher prevalence of CD163+ macrophages in tumor-infiltrating cells from resected tumors compared to peripheral blood, promoting T lymphocyte proliferation and proinflammatory cytokine production." (PMID 40136652, 2025). "Histological evaluation confirmed the diagnosis of cutaneous histiocytic sarcoma, with tumor cells expressing CD163 and CD68." (PMID 40901224, 2025). "Immunofluorescence assays corroborated these findings, revealing a reduced percentage of CD86+ M1 macrophages and an increased percentage of CD163+ M2 macrophages and CD4+Foxp3+ Treg cells in mutated tumor tissues." (PMID 40384867, 2025). "These tumours also express tumour‐associated genetic markers (e.g., CD44v6, CDX2, BRAF) and immune markers (e.g., CD68, CD163), alongside characteristics like CpG island methylator phenotype and KRAS mutations." (PMID 40444502, 2025).
tumor (continued). "In contrast, the fraction of CD163+CD86+ M2-like macrophages was significantly increased in all 4 of 4 tumor entities compared to that seen in NMC aspirates." (PMID 40274631, 2025). "Given LGALS9 upregulation in immune-hot tumors, we assessed tumor-associated macrophages via CD68 (pan-macrophage marker) and CD163 (M2 macrophage marker) IHC to evaluate their contribution to an immunosuppressive microenvironment." (PMID 41332664, 2025). "Increased expression of CD163, CD68 and CD3 (p < 0.0001, p = 0.0015 and p = 0.0024 respectively) was associated with partial tumor resection (PR)." (PMID 41044688, 2025). "CD163‐GNPs preferentially target M2 macrophages, synergize with radiotherapy to reduce tumor growth." (PMID 41201063, 2025). "The fraction of CD8+ T cells was lower, while the infiltration rate of immunosuppressive CD56+CD16− NK cells and CD163+CD86+ M2-like macrophages were significantly enriched in all 4 tumor entities." (PMID 40274631, 2025). "To spatially characterize TIL-B infiltration and interaction with other immune subsets, we compared five TIL-B-poor and six TIL-B-rich OCSCC using an m-fIHC panel optimized for tumor cells, CD163+ macrophages, CD4+, CD8+, and FoxP3+ regulatory T-lymphocytes." (PMID 39796740, 2025). "Disruption of CD8+ T cells accelerates tumor growth, while depletion of CD163+ TAMs inhibits tumor progression." (PMID 41357670, 2025). "This also undermines the positive prognostic relevance of CD68+CD163+ macrophages in the stromal compartment of normal tissue surrounding the tumor." (PMID 40498004, 2025). "Next, we visualized changes in CD163+ immune cells in the tumor nest and tumor stroma during tumor progression using Sankey diagrams of patient-matched tissue samples." (PMID 39751847, 2025). "In another study, TAM (CD68+) infiltration in LC tumors, including tumor-promoting M2 macrophages (CD163+) and lymphocytes (CD3+), was significantly reduced after RESV treatment." (PMID 40948874, 2025). "The observation that CD163 was upregulated in both co-culture conditions suggests that tumour-macrophage interactions broadly favour M2 polarization, although STn expression appears to selectively enhance the CD206 axis." (PMID 41152402, 2025). "CD163 expression in tumor stroma was investigated in three studies: two (66.7%) out of three found more favorable outcomes, and the third (33.3%) reported shorter survival in patients whose tumors showed high stromal CD163 expression." (PMID 39904885, 2025). "The elevation of CD163+ macrophages in regions with high‐grade dysplasia confirms the role of TAM‐2 as tumor‐promoting immune cells also in IPMNs." (PMID 40736369, 2025). "Some exhibited high densities of both CD8+ and CD163+ cells in the TC and IM (HH/HH), while others displayed various combinations of these cell types across tumor compartments (the “Rest” group)." (PMID 41374956, 2025). "Both intra-tumoral and peritumoral CD163+ macrophage counts increased with advancing tumor stage, with the most pronounced relative increase observed in the peritumoral compartment." (PMID 41007741, 2025). "CD163 cell density in Tumor Resection specimens after IT (mean 1204 cells/mm2) was significantly (p=0.036) higher compared to Heathy Gingiva Controls (mean 4 cells/mm2) as well as compared to OSCC Resection specimens without IT (mean 192 cells/mm2)." (PMID 40297579, 2025). "Three human CRC specimens were selected to validate such discovery by assessing the co-expression of TREM2 and macrophage marker CD163 in tumor tissue." (PMID 39744236, 2025). "Taken together, these data suggest activin co-localization in the TME promotes CD163 and FAPα expression to facilitate a tumor- tolerant environment." (PMID 40075112, 2025). "TAMs exhibit functional plasticity, polarizing toward either a pro-inflammatory, antitumor phenotype (M1, CD68-positive) or an anti-inflammatory, tumor-promoting phenotype (M2, CD163-positive)." (PMID 41239536, 2025).
tumor (continued). "Intriguingly, CD163+ cells were concentrated only at the periphery of the primary tumour, suggesting that M2 macrophages were recruited to, but did not infiltrate the tumour." (PMID 41315643, 2025). "Supporting this idea, the tumor-infiltrating CD8/CD163-positive cell ratio was significantly higher in responding patients than in patients without disease control (p = 0.0228)." (PMID 39652104, 2025). "To summarize, distribution of CD163+ immune cells is similar across tumor sites (PT, LNM and DM) and observed changes during tumor progression were not significant." (PMID 39751847, 2025). "In the 3D model, M2-polarised macrophages (CD68 + CD163 + TMEM119 -) that had been validated by ICC were co-cultured with tumour cells." (PMID 40420192, 2025). "As Chil3 is expressed not only by M2 macrophages but also by neutrophils and some other cells, it was important to confirm M2 macrophage infiltration into tumor tissue by detecting CD163 cellular receptors." (PMID 40918453, 2025). "In OS, the TME exhibits extensive macrophage infiltration, predominantly myeloid CD163+ cells, potentially facilitating tumor immune evasion." (PMID 40534850, 2025). "Our findings on CD68+CD163+CD206+ M2-type macrophages suggest a potential relevance of these macrophages in the stromal compartment of tumor distant normal tissue (p = 0.171)." (PMID 40498004, 2025). "We performed immunohistochemical examination of CD4, CD8, CD68, and CD163 subpopulations in tumor sections." (PMID 41256864, 2025). "The CD163+ macrophages are thought to counteract tumor immunity by enhancing immunosuppressive mechanisms." (PMID 40427615, 2025). "Based on their research, Jeong and colleagues found that invasive breast cancer (IBC) patients had bigger tumors and a worse prognosis when CD163+ M2-like macrophages had infiltrated into tumor nests." (PMID 40422244, 2025). "Consistently, our IHC analysis demonstrated prominent colocalization of paucimannosidic epitopes with anti-inflammatory (CD163+) macrophages known to originate from tumor-infiltrating monocytes." (PMID 39947398, 2025). "CD163, widely applied as an immunohistochemical TAM marker, is associated with tumor infiltration and invasion, with expression levels correlating with tumor stage, nodal involvement, and metastasis." (PMID 40948759, 2025). "Histological examination further confirmed a decreased tumor burden and reduced infiltration of M2 macrophages (CD163 and F4/80 double-positive cells) in FABP5 knockout tumors." (PMID 41035647, 2025). "Moreover, the immunohistochemical profile of the tumor microenvironment revealed that the expression content of tumor-associated macrophages (CD163, CD68) and fibroblasts (SMA) differs between cancerous and precancerous tissues which may regulate the disease development." (PMID 40416971, 2025). "The expression of CD163 by macrophages changes with macrophage proximity to tumour cells has a small adjusted P-value (7.7×10-5) and large coefficient (0.061; 99th percentile of all significant CCMs) relative to other CCMs." (PMID 40674581, 2025). "TAMs, often characterized by a high expression of CD47 and CD163, contribute to immune evasion and tumor progression." (PMID 39857116, 2025). "Evidence of this Tumour-Macrophage-CD163 CCM is observed when using both minimum distance and abundance as metrics to quantify cell proximity, consistent with the strong concordance observed across all relationships for the two spatial metrics." (PMID 40674581, 2025). "In group 0, several immune checkpoint and pro-inflammatory genes, including PDCD1LG2 (PD-L2), CD274 (PD-L1), HLA-A, CXCL10, and CD163, displayed relatively high expression, suggesting a more inflamed tumor microenvironment." (PMID 41517303, 2025). "CD163-positive macrophages are considered to contribute to tumor progression, especially by promoting angiogenesis, tumor cell proliferation, and survival." (PMID 40136662, 2025).
tumor (continued). "Immunohistochemical staining for CD163 and CSF-1 was performed, and differences in immunohistochemical results among the three tumor components were analyzed." (PMID 39488822, 2025). "Macrophages_LYVE1 also expressed high levels of LYVE1, RNASE1, STAB1, CD163, and MARCO, which are associated with macrophage function and tumour immunosuppression." (PMID 40759637, 2025). "Markers for T-cell subsets (CD4, CD8), macrophages (CD68, CD163), granulocyte cells (CD11b), tumor cells (PanCK), vasculature (CD31), and epithelium (cytokeratin) were clearly visualized in the CODEX fluorescent images." (PMID 39969434, 2025). "CD68+ cells predominantly localized to peripheral tumor regions, while CD163+ cells formed diffuse clusters in central tumor zones and around peripheral vessels." (PMID 40843751, 2025). "CD163, an anti-inflammatory marker, is typically downregulated as macrophages shift to a pro-inflammatory state in response to tumour cells." (PMID 40674581, 2025). "While CD68+ macrophages were mostly found in the intratumoral region, the CD163+ macrophages prevailed within the tumor stroma." (PMID 41150099, 2025). "The present study revealed that TWEAK expression was localized in the immune cells and the stroma surrounding the tumor margin of CRLMs, which was correlated with the infiltration of Th17 cells and CD163‐positive macrophages." (PMID 40629930, 2025). "Among these markers, CD68 and CD163 are two important indicators that are related to the tumor microenvironment (TME)." (PMID 41256322, 2025). "CD163+macrophages engage in complex cellular communication networks with various cell types, potentially influencing the tumor immune microenvironment by modulating multiple signaling pathways involved in antigen processing and T cell activation." (PMID 40707992, 2025). "In order to evaluate the expression levels and topographic distribution profiles of CD4, CD8, Foxp3, CD68, CD163, and CD11c, tissue microarrays of the invasive front as well as the tumor core of BCC and cSCC samples were analyzed." (PMID 41068337, 2025). "IHC analysis of human GBM specimens revealed a positive correlation between ENO1 expression and CD163+ M2-TAM infiltration in tumor stroma." (PMID 41353343, 2025). "Immunohistochemistry on tumour biopsy specimens before CAR T‐cell infusion revealed elevated levels of CD163+ and TREM2+ cells in non‐responders compared to responders (p = .0092 and p = .0350, respectively)." (PMID 40268516, 2025). "TC demonstrated an immune-rich profile representing abundant tumor-associated CD8+ lymphocytes, CD68 and CD163+ macrophages." (PMID 39936166, 2025). "A representative image of this relationship demonstrates that average CD163 abundance in macrophages is lowest when macrophages are close to tumour cells." (PMID 40674581, 2025). "Increased density of CD163+ TAMs was primarily observed in the central tumor regions, where they formed diffuse infiltration, often associated with small-caliber blood vessels or areas of fibrotic remodeling." (PMID 40843751, 2025). "Complementary tissue immunofluorescence assays further demonstrated an upregulation of the M1 macrophage marker CD86 and a concurrent downregulation of the M2 marker CD163 in RP-6306-treated tumor tissues." (PMID 40664640, 2025). "Immunohistochemical analysis revealed that PD-1 expression in tumor tissues of the microbial treatment group was significantly higher than that in the control group (p < 0.05), whereas CD163 expression was significantly decreased (p < 0.05)." (PMID 41562055, 2025). "Immunohistochemical staining identified CD68+ and CD163+ macrophages both within the tumor and in the surrounding stroma." (PMID 41007741, 2025). "Cases with macrophage-enriched tumor immune microenvironments (Mac-enriched) often lack tumor cells and are rich in immune cells, particularly CD163+ macrophages and CD8 T cells." (PMID 40426926, 2025).